DKK4 (dickkopf Wnt signaling pathway inhibitor 4)
Diseases named in the same sentence as DKK4 in open-access papers (continued):
Sharing a sentence is not in itself a finding about the gene and the disease.
cancer (22 papers, 2006 to 2025). A tumor composed of atypical neoplastic, often pleomorphic cells that invade other tissues. "In contrast, a study reported the association of DKK4-mediated positive regulation of glucose and ROS and resultant P-gp upregulation; however, the types of cancer cells that upregulate DKK4 levels remain controversial." (PMID 37375753, 2023). "In CRC, a few studies with limited samples revealed that DKK4 was upregulated in cancer, but little is known about the association of DKK4 expression and CRC prognosis, and the molecular mechanism remains unclear." (PMID 36181792, 2022). "DKK-4 plays a pivotal role with profound implications for development, cancer, and disease progression." (PMID 39860164, 2025). "The results indicate that DKK4 expressed in CRC cancer cells strongly induces the formation of Vimentin+α-SMA+ fibroblasts and α-SMA+ MYH9+ myofibroblasts in cancer stromal tissues in mouse models." (PMID 38519641, 2024). "Increased expression of DKK4 in cancer stem cells enhanced the expression of F-actin and MYH9 in fibroblasts but did not further change the morphologies of fibroblasts and myofibroblasts." (PMID 38519641, 2024). "To determine the underlying mechanism by which DKK4 promotes CRC metastatic abilities, we initially determined the characteristics of CRC stem cells and cancer cell lines in culture conditions." (PMID 38519641, 2024). "The increased expression of DKK4 restricts the expansion of xenografts derived from all cancer cells tested." (PMID 38519641, 2024). "Cancer stem cells and cancer cell lines overexpressing DKK4 were intraperitoneally and subcutaneously injected into mice." (PMID 38519641, 2024). "All the results suggest that DKK4 displays essential functions in the microenvironments of cancer tissues for CRC metastatic abilities." (PMID 38519641, 2024). "For further determination of the metastatic abilities of cancer stem cells and cancer cell lines, cells with reduced DKK4 expression were intraperitoneally injected into mice." (PMID 38519641, 2024). "The total protein levels and the active form of β-catenin were significantly enhanced in fibroblasts cocultured with cancer stem cells and cancer cell lines with reduced expression of DKK4." (PMID 38519641, 2024). "First, cancer stem cells (1597) and cancer cell lines (SW480) with reduced expression or overexpression of DKK4 were intravenously administered to mice." (PMID 38519641, 2024). "DKK4 overexpression in CRC cancer cells dramatically reduced the protein expression of β-catenin in stromal cells in CRC xenografts." (PMID 38519641, 2024). "The results showed that fibroblasts cultured in media from DKK4-expressing cancer stem cells and cancer cell lines presented a large, star shape and had cytoplasmic stress fibres." (PMID 38519641, 2024). "Dkk4 is closely related to cancers where its expression is regulated differently in distinct types of cancers." (PMID 39872377, 2024). "In comparison, the fibroblasts cultured in the media from cancer stem cells and cancer cell lines with reduced expression of DKK4 had an elongated spindle shape with much fewer stress fibres and were small in diameter." (PMID 38519641, 2024). "The examinations showed that β-catenin was highly enhanced in the stromal cells in CRC xenografts generated from cancer stem cells and cancer cell lines with reduced expression of DKK4." (PMID 38519641, 2024). "The results suggest that the secretion of DKK4 from cancer stem cells and cancer cell lines can inhibit the Wnt/β-catenin signalling pathway via reduced β-catenin protein in fibroblasts." (PMID 38519641, 2024). "Many investigators have examined the role of DKK4 expression in several cancers, but there are still controversies about the role of DKK4 in cancer, depending upon the cancer type." (PMID 37096225, 2023). "Dickkopf 4 (DKK4) is known as a Wnt/β-catenin pathway inhibitor, and its upregulation was reported in several cancers." (PMID 37096225, 2023).
cancer (continued). "The dysregulation of DKK4 plays a significant role in the process of initiation and metastasis in various cancer types." (PMID 36181792, 2022). "Many studies on DKK4 have been done by now; however, the mechanism and molecular role of DKK4 in the cancer or non‐cancer diseases remains elusive." (PMID 33586359, 2021). "Although DKK-4 is the least studied member, its implication in cancer is sustained by small but growing evidence." (PMID 34451907, 2021). "In this review, we have conducted the literature search on DKK4 and summarized its function and regulation mechanism in cancer and non‐cancer tissues." (PMID 33586359, 2021). "Along this line, elevated expression of DKK4 was observed in both colon and kidney cancer tissues and was reported to promote cancer cells’ invasion, migration and progression." (PMID 33586359, 2021). "Several cancer-promoting genes were uperegulated (Ctgf, H19, Mmp12, Mybl1, Vnn1) while cancer inhibiting genes (Cish, Dkk4, Onecut1, Scara5, Socs3, Wif1) were suppressed." (PMID 26200659, 2015). "All the loci interrogated were essentially unmethylated in control CD19+ B cells of five healthy individuals with the exception of DKK4, which was found to be methylated (36; 33 to 39) to a level very similar to that in the cancer samples." (PMID 22672427, 2012). "Therefore, the mRNA expression or protein levels of genes involved in the Wnt/β-catenin signalling pathway in fibroblasts after culture with the overexpression of DKK4 in cancer stem cells and cancer cell lines were determined." (PMID 38519641, 2024). "Thus, DKK4 expression in cancer stem cells and CRC cell lines can transform fibroblasts into fibroblasts and myofibroblasts containing stress fibres." (PMID 38519641, 2024). "LiCl treatment strongly reduced fibroblast transformation by DKK4-overexpressing cancer cells." (PMID 38519641, 2024). "Among them, DKK4 expression was decreased mainly in differentiated cancer cells." (PMID 38519641, 2024). "Moreover, the total protein levels and active form of β-catenin were dramatically reduced in fibroblasts cultured in conditional media obtained from cultured cancer stem cells and cancer cell lines with overexpressing DKK4." (PMID 38519641, 2024). "The results indicate that differential effects of DKK4 on the growth of primary CRC cancers might be that different types of CRC cancers are respectively required a specific activation of Wnt/β-catenin signalling pathways." (PMID 38519641, 2024). "DKK4 is a secreted glycoprotein that has potential as a serum biomarker for cancer detection." (PMID 37070251, 2023). "Although increasing evidence has revealed that DKK4 promotes cancer progression and the acquisition of resistance to chemotherapy, some reports showed that DKK4 inhibited cell proliferation, migration, and invasion in cancer." (PMID 37096225, 2023). "DKK4 presents inconsistent expression and plays different roles in different cancers." (PMID 36181792, 2022). "Contrary to above cancers, some research showed that DKK4 reduced in HCC." (PMID 33586359, 2021). "Till now, the expression pattern and mechanism of DKK4 in cancer was still obscure." (PMID 28666421, 2017). "Thus, DKK4 expression in CRC cancer cells reduces the expression of β-catenin in stromal cells in cancer tissues, resulting in the transformation of fibroblasts to form stress fibre-containing fibroblasts and Vimentin+F-actin+MYH9+α-SMA+ myofibroblasts in cancer stromal tissues." (PMID 38519641, 2024). "However, little is known about the function of DKK4 in cancer." (PMID 16584549, 2006). "The results showed that DKK4 highly expressed in CRC stem cells and greatly decreased its expression in cancer cells derived from the differentiation of CRC stem cells." (PMID 38519641, 2024). "The cancer cell lines SW480 and SW620, with reduced DKK4 expression, were subcutaneously injected into mice." (PMID 38519641, 2024). "Thus, DKK4 might act as a tumour suppressor gene or an oncogene in cancers." (PMID 38519641, 2024).
cancer (continued). "We identified macrophages instead of all immune cells in the xenografts and found that macrophages were not altered in the CRC xenografts generated with CRC stem cells and cancer cell lines with reduced expression of DKK4 (data not shown)." (PMID 38519641, 2024). "Therefore, to check for correlation if any, between DKK4, β–catenin, Wnt3a and c-Myc expression in HCC, we searched the ONCOMINE human cancer genomics database." (PMID 27272409, 2016). "On the other hand, 12 of the NMR-missing genes in this pathway, such as Dkk4, Sox17 and Ccnd3, have not been reported to be related to any disease including cancer." (PMID 24565050, 2013). "The differential growing phenotypes obtained from the three CCSCs in mice could not be explained by the DKK4 protein levels in CCSCs and may be due to the specific characteristics of the cancer tissues that are used to derive CCSCs." (PMID 38519641, 2024). "TFAP2E normally represses DKK4 promoter activity through direct binding, hence, low or no TFAP2E expression leads to DKK4 overexpression seen in CRC cell lines and cancer specimens." (PMID 25622259, 2015). "All the tests indicate that the expression of DKK4 in CRC cells could not change the distributions and features of blood vessels, neural tissues, and immune cells in the microenvironments of cancer tissues." (PMID 38519641, 2024).
DKK4 also shares sentences with these, for which no sentence is quoted: renal cell carcinoma (3 papers); hepatoblastoma (2); atherosclerosis (1); benign tumors (1); breast tumours (1); clear cell renal cell carcinoma (1); colorectal adenocarcinoma (1); diabetes (1); digestive system neoplasm (1); kidney cancer (1); liver cirrhosis (1); lung adenocarcinoma (1); Medullary thyroid carcinoma (1); neuroblastoma (1); non-small cell lung carcinoma (1); Oral Squamous Cell Carcinoma (1); sarcoma (1); serous ovarian cancer (1).